ATM (ATM serine/threonine kinase)
Diseases named in the same sentence as ATM in open-access papers (continued):
Sharing a sentence is not in itself a finding about the gene and the disease.
tumor (continued). "Thus, in addition to well-established roles in tumor suppression, these findings identify a role for ATM in tumor progression." (PMID 26030852, 2015). "IHC staining data obtained from tumor tissues also supported our hypothesis by showing a higher number of ATM and CHK1 stained cells in the A549sc xenografts than in the A549IL-6si xenografts." (PMID 26313152, 2015). "In summary, we have identified a tumor promoting activity for ATM." (PMID 26030852, 2015). "This supports the hypothesis that loss of ATM activity gives rise to more aggressive, EMT-rich tumours due to increased tumour initiating cell potential." (PMID 26220524, 2015). "For instance, while fractional abundance of ATM, NRAS and IGF1R mutations in the primary tumour was 35%, 20% and 2%, respectively, the prevalence of these mutations in the corresponding plasma samples was 0.05, 0.07 and 0.07%, whereas in the sputum, mutations fractions were 0.04, 0.03 and 0.03%." (PMID 26374070, 2015). "Nevertheless, the clinical data presented here does suggest that high ATM/DNA-PKcs/ATR expressing tumours may be less sensitive to chemotherapy." (PMID 26674120, 2014). "A total of 186 tumours were suitable for analysis of ATM nuclear expression." (PMID 26674120, 2014). "The ATM protein, a serine/threonine kinase involved in DNA double-strand break repair, is also involved in DNA repair and its inactivation is a highly destabilizing event for the cell, promoting the progression of neoplastic disease." (PMID 25091577, 2014). "In a separate cohort, the adverse prognostic significance was also observed at the mRNA level for ATM and DNA-PKcs implying that high protein levels may be related to high ATM and DNA-PKcs mRNA levels in tumours." (PMID 26674120, 2014). "Using [18F]-FAC, a dCK-specific positron emission tomography (PET) probe, we visualized and quantified dCK activation in tumor xenografts after IR, indicating that dCK activation could serve as a biomarker for ATM function and DNA damage response in vivo." (PMID 25101980, 2014). "ATR deficiency was significantly associated with menopause (P = 0.025), strong expression of ATM (P = 0.017) and MRE11 (P = 0.040) with pre-menopausal SOC, strong expression of MRE11 (P = 0.016) with low tumor grade, and strong expression of BRCA1 (P = 0.015) with early clinical stage." (PMID 24752797, 2014). "GC patients with negative ATM IHC were associated with old age, large tumor size, well to moderately differentiated type, and intestinal type of Lauren’s classification." (PMID 24324828, 2013). "For example, miR-101 could sensitize human tumor cells to radiation by targeting ATM and DNA-PK catalytic subunit (DNA-PKcs) to inhibit DNA repair." (PMID 23614048, 2013). "Subsequently it has been demonstrated that treatment with antioxidants could delay tumor formation in ATM null mice and rescue other aspects of development." (PMID 23532176, 2013). "Mice expressing hypomorphic Mre11 complex alleles recapitulate most DDR related aspects of ATM deficiency but are not tumor prone and do not exhibit the same oxygen-dependent phenotypes observed in the absence of ATM." (PMID 23532176, 2013). "It is therefore likely, at least in mice, that ROS signaling via ATM is largely intact and this could be sufficient for tumor suppression in Mre11 complex mutants." (PMID 23532176, 2013).
tumor (continued). "Our current findings suggest for the first time that metformin can function as an antifolate chemotherapeutic agent that induces the ATM/AMPK tumor suppressor axis secondarily following the alteration of the carbon flow through the folate-related one-carbon metabolic pathways." (PMID 22837425, 2012). "Not long after the initial characterisation of these pathways, the functional significance of the DDR activation was revealed by genetic studies indicating that ATM and Chk2 were critical tumour suppressors downstream of oncogenes including H-RasV12, Mos, Cdc6, and cyclin E." (PMID 22240795, 2012). "We found that the association of disease-free survival with ATM expression is independent of tumour stage, location, use of chemo/radiotherapy, gender, KRAS/BRAF mutation status, microsatellite instability or chromosomal instability." (PMID 23154512, 2012). "The role of ATM in regulating Myc-induced tumor suppressive DDR, was also confirmed in a mouse model of skin cancer suggesting that the relevance of this pathway in suppressing Myc-induced tumors suppression is not restricted to hematological malignancies, but extends to solid tumors." (PMID 22373487, 2012). "The ATM positivity was defined as greater than 30% ATM (+) tumor cells in whole tumor areas." (PMID 22485171, 2012). "In addition, tumour diameter (≥4 cm; OR = 1.848; p = 0.014) and age (OR = 1.005: p = 0.006) were also related to p-ATM expression." (PMID 22323184, 2012). "We have shown before that constitutive DNA damage signaling represented by H2AX-Ser139 phosphorylation and ATM activation in untreated normal and tumor cells is a reporter of the persistent DNA replication stress induced by endogenous oxidants, the by-products of aerobic respiration." (PMID 22067284, 2011). "We present here our findings of the contribution of p53Ser18 to ATM-mediated tumor suppression." (PMID 21980358, 2011). "Jet-lag promptly desynchronizes the central clock-SNS-peripheral clock axis, abolishes the peripheral clock-dependent ATM activation, and activates myc oncogenic potential, leading to tumor development in the same organ systems in wild-type and circadian gene-mutant mice." (PMID 20539819, 2010). "In this study, we were interested in testing the new hypothesis that targeting DNA-PKcs and ATM with one miRNA could sensitize tumor cells to IR." (PMID 20617180, 2010). "A total of 56 molecules are annotated as affecting neoplasia and eight of these are dysregulated over 1.5 fold in Ad12-TC compared to Ad5-TC: down-regulation of ATM, CD19, CD3G, GADD45B, HPSE, TFAP2A and TFPI was observed, whereas levels of EGFR were found to be up-regulated." (PMID 19200380, 2009). "Synthetic lethal interactions between the FA pathway and other DNA damage response genes such as ATM, PARP1 and NBS1 have been identified recently, stimulating interest in determining if FA pathway inhibitors would selectively target tumor cells deficient in these genes." (PMID 20043851, 2009).
tumor (continued). "The role of ATM in neoplasia is not due to dysregulated levels of expression: mutated ATM plays a role in neoplasia and the mouse ATM gene decreases the development of neoplasia by acting through V(D)J recombination." (PMID 19200380, 2009). "Among tumor suppressors, ATM, a major regulator of the cellular response to DNA double-strand breaks, may be a key factor in the DDR pathway." (PMID 18570662, 2008). "On the other hand, observation of LOH outside the ATM locus may indicate the involvement of other tumour-suppressor genes in this disease." (PMID 14735203, 2004). "The antitumor effects of BMN673 against ATM-deficient CRC cells were confirmed in vivo by employing a subcutaneous xenograft model in nude mice, wherein BMN673 administration significantly inhibited tumor growth, as evidenced by reduced tumor volumes and weights." (PMID 41266732, 2025). "In addition, ATM inhibition could reverse the immune “cold phenotype” of tumor cells by activating the TNF-α/STAT1 signaling pathway and up-regulating the expression of MHC-I molecules." (PMID 40825766, 2025). "Finally, we explored the connection between ATM expression and tumor stage." (PMID 40144209, 2025). "Mutational signature analyses showed the pooled somatic variants from the LLGL2-inactivated tumours were more like the ATM-inactivated tumours as opposed to the PALB2-inactivated tumours, with GEL-Ovary_common_SBS5 and GEL-Ovary_common_SBS1+18 signatures prominent." (PMID 39794353, 2025). "Although we are not able to confirm the loss of ATM protein in the absence of immunohistochemistry data, this provides a plausible explanation for the long-term response of this tumour, because PLD-induced DNA DSBs would not be effectively repaired in the absence of functional ATM and DNA-PK." (PMID 40382524, 2025). "In these cases, combining SBRT with DNA-PK or ATM inhibitors may enhance tumor radiosensitivity." (PMID 40725389, 2025). "Furthermore, in the attempt to discover acquired genetic vulnerabilities, we find that ATM but not ATR inhibition overcomes PARP inhibitor (PARPi) resistance in H2AX-deficient tumours by interfering with CtIP-mediated fork protection." (PMID 38789420, 2024). "Moreover, BLM emerges as a regulator of the tumor immune microenvironment, inducing MHC-I expression in a manner dependent on ataxia-telangiectasia mutated/ataxia telangiectasia and Rad3-related–NF-κB (ATM/ATR–NF-κB) signaling." (PMID 39106105, 2024). "Second, we cannot rule out that ATM variants found in circulating tumor cell DNA profiles could be related to clonal hematopoiesis rather than mutations in the tumor of interest." (PMID 38260227, 2024). "However, since normal tissue cells use the same DDR and DNA repair factors and mechanisms, it remains to be shown to what extent the inhibition of such integral components as ATM, DNA-PKcs or Ku70/Ku80 will be able to induce radiosensitisation in a sufficiently tumour-specific manner." (PMID 39478631, 2024).
tumor (continued). "From our work, going forward, tumour-targeting prodrugs hydrolyzing CD13 should avoid targeting ATM and its downstream targets; not doing so may cause impaired ATM signaling and subsequent reduced CD13 expression, hindering the efficacy of the therapeutic." (PMID 38933336, 2024). "However, increased expression of ATR and ATM proteins was observed in insensitive tumor cells." (PMID 37305685, 2023). "The T-cell compartment associated with the low ATM expressing tumor cells showed GO term enrichment for “Interferon γ (IFN-γ) signaling” (p = 0.00019) and “T-cell-mediated cytotoxicity pathway” (p = 0.017) as compared to the T cells from high ATM expressing tumor cells." (PMID 36949040, 2023). "Therefore, our results from three murine tumor models strongly suggested that anti-Gal-9 therapy combined with ATM inhibition significantly reduces tumor growth and enhances the survival of host mice, even in poorly immunogenic tumor models that are refractory to current immune checkpoint therapy." (PMID 36778120, 2023). "Thus, tumours with ATM GAs may be sensitive to a synthetic lethality approach with ATR inhibitors, with or without the addition of immune checkpoint inhibitors." (PMID 37821580, 2023). "In addition, we demonstrate a similar frequency of germline variants among patients with tumor variants in the moderate risk gene ATM, which has not been examined extensively in previous studies." (PMID 36261688, 2023). "Furthermore, we hypothesize that ATR inhibition results in anti-tumor activity in DDR alterations beyond ATM, such as BRCA1/2 and others." (PMID 37277454, 2023). "Notably, a patient with advanced CRPC whose tumor had biallelic ATM LOF and was positive for ATM protein had a pathogenic missense mutation in the phosphatidylinositol 3-kinase (PI3K) regulatory domain of ATM (p.R3008H), which is not expected to result in loss of ATM expression." (PMID 37277454, 2023). "Many of the most frequent actionable alterations within TMB-H tumors were within tumor suppressor pathways (PIK3CA/PTEN, CDKN2A, BRCA1/2, NF1, ATM, and TSC1/2), suggesting that many variants may be passenger rather than driver alterations in the setting of highly altered tumors." (PMID 36602798, 2023). "Therefore, inhibition of ATM proteins is an alternative approach to suppressing tumor growth." (PMID 36902170, 2023). "Herein, we tested the potential of this drug delivery system that encapsulates an ATM inhibitor to target and sensitize mammospheres—considered as a model system of BCSCs—to an anticancer drug, while having a comparably lower cytotoxic effect against bulk tumor cells." (PMID 36900267, 2023). "In addition, it was shown that HMGB3 protein could bind to chemotherapeutic drug–induced damage DNA, leading to the activation of ATM‐and Rad3‐related protein, thus promoting the drug resistance of tumor cells." (PMID 35754798, 2022).
tumor (continued). "In addition, for ATM, an important checkpoint gene for DNA double-strand breaks (DSBs), inhibiting it could make tumor cells fail to detect DSBs and thereby aggravate DNA damage, promoting cell apoptosis." (PMID 35281113, 2022). "The number and locations of tumors, quadrant of tumors, regularity of tumor margins, presence of blood flow signals, presence of posterior echo attenuation, presence of calcification, histological grade, molecular typing, and mutations of BRAF, ATM, and PALB2 were irrelevant factors (P > 0.05)." (PMID 35255911, 2022). "The reduced effectiveness of ATM inhibition concerning radiosensitization of HPV+ cells argues against a clinical exploration of this approach since ATM inhibition also induces severe radiosensitization in non-tumor cells, which in sum likely results in an unfavorable therapeutic ratio." (PMID 35719921, 2022). "Elevated levels of ATM expression may facilitate tumor resistance to radiation and chemotherapy." (PMID 35744942, 2022). "To further confirm ATM‐associated DDR participates in the citrate‐induced senescence processes in tumor cells, we investigated whether citrate‐induced senescence in tumor cells can be prevented by blocking DNA damage activation with the ATM‐specific pharmacological inhibitor KU55933." (PMID 34747157, 2022). "This may mean that identified hits do not fully reflect the drivers of cell death in tumours harbouring specific genetic defects, such as mutations in ATM, that are likely to be targeted with ATR inhibitors in the clinic." (PMID 34329458, 2021). "Overall, no tumor with ATM-BAL alone exhibited a CSig3(+) DNA mutation profile." (PMID 34877933, 2021). "Hence, we speculated that RNF168 may participate in this process by ATM, and therefore activate the physiology and proliferation of tumor cells." (PMID 33493132, 2021). "Interestingly, in some tumor cells, ATM signaling and function are upregulated." (PMID 34070860, 2021). "Therefore, ATM is often considered a major tumor suppressor." (PMID 34070860, 2021). "Besides, Autophagy induced by ATM is also of great significance in the context of tumor research." (PMID 34421351, 2021). "Furthermore, we believe these findings are likely to have clinical ramifications since aberrant regulation of MYBL2 may affect the sensitivity of tumour cells to inhibitors of the ATM‐dependent DNA damage response." (PMID 33779025, 2021). "Although several studies showed that ATM inhibition resulted in CSC eradication loss of ATM function serves as a double-edged sword as it might promote malignant transformation and accelerate tumor growth." (PMID 34638302, 2021). "As such, the PIDDosome should exert tumor‐suppressive functions that may explain observations of increased rates of tumor formation in mice lacking caspase‐2, challenged by oncogenic drivers such as MYC or ERBB2, or concomitant ATM loss." (PMID 33225610, 2020). "AZD0156 is a strong radio-sensitizer that recently has been demonstrated to inhibit tumor growth after radiation treatment of lung xenograft; in addition, a combinatory effect with PARP inhibitors (olaparib) is under study since sensitivity to these drugs is related to ATM deficiency." (PMID 32932697, 2020).